ALKBH5 (alkB homolog 5, RNA demethylase)
Diseases named in the same sentence as ALKBH5 in open-access papers (continued):
Sharing a sentence is not in itself a finding about the gene and the disease.
pancreatic cancer (continued). "The present research about ALKBH5-mediated m6A demethylation mainly focuses on the pathogenesis of multiple tumors, including cancers of the pancreas, ovary, lung, and breast." (PMID 33364952, 2020). "More recently, mechanistic investigations have documented another ALKBH5-mediated inhibition of the most common form of pancreatic cancers, the pancreatic ductal adenocarcinoma, through the ALKBH5 dependent-Wnt inhibitory factor one pathway." (PMID 33511112, 2020). "Downregulation of the m6A eraser protein ALKBH5 was correlated with poor prognosis in pancreatic cancer." (PMID 32742465, 2020). "To conclude, ALKBH5 carries suppressive effects on certain tumors to provide mounting evidence to be an excellent new prognostic marker for pancreatic cancers." (PMID 33511112, 2020). "He et al47 revealed that ALKBH5 inhibits the motility of pancreatic cancer by downregulating long non-coding RNA KCNK15-AS1 methylation." (PMID 32742465, 2020). "In pancreatic cancer, ALKBH5 relies on the demethylation of Wnt inhibitory factor 1 (WIF-1) and the activation of Wnt signal to inhibit tumorigenesis and make tumor cells more sensitive to chemotherapy." (PMID 33552994, 2020). "These modifications can be written by METTL3 or METTL14 and can be erased by ALKBH5 and regulate the tumorigenesis of leukemia, pancreatic cancer, endometrial cancer and gastric cancer." (PMID 31722709, 2019). "In pancreatic cancer, the expression of ALKBH5 is reduced, resulting in elevated m6A level and reduced expression of tumor suppressor gene KCNK15-AS1, leading to enhanced migration and invasion of pancreatic tumor cells." (PMID 31801551, 2019). "However, in pancreatic cancer, ALKBH5 regulates the expression of Wnt inhibitory factor 1 (WIF-1) and inhibits the downstream Wnt signaling pathway." (PMID 40603319, 2025). "Analysis of gene expression and copy number variation (CNV) data of pancreatic cancer patients in the TCGA database reported that patients with ALKBH5 CNV have a worse prognosis and that increased expression of ALKBH5 is positively correlated with activation of AKT pathways." (PMID 40448344, 2025). "In pancreatic cancer, ALKBH5 has been shown to stimulate tumor growth." (PMID 40271153, 2025). "Similarly, in pancreatic cancer, ALKBH5 has been shown to inhibit tumor progression by affecting the Wnt signaling pathway." (PMID 38798700, 2024). "We show increased m6A-modifications of HDAC4 in ALKBH5 silenced cells that may influence HIF-α protein stability in our hepatoma model as previously reported in pancreatic cancer." (PMID 38227578, 2024). "However, ALKBH5 is downregulated in bladder cancer, pancreatic cancer, and osteosarcoma, and ALKBH5 overexpression markedly reduces the proliferative, migratory, and invasive features of those cancer cells 13-15." (PMID 37325047, 2023). "In addition, overexpressing HIF1a promoted the transcription of ALKBH5 in hypoxic pancreatic cancer cells." (PMID 37149664, 2023). "In pancreatic cancer, ALKBH5 plays a pro-oncogenic role and ALKBH5 overexpression can promote tumor progression by downregulating potassium two-pore domain channel subfamily K member 15 and WISP2 antisense RNA 1 (KCNK15-AS1), an oncogene, to promote tumor growth invasion and metastasis." (PMID 37063421, 2023). "Additionally, ALKBH5‐mediated m6A demethylation reduces the mRNA stability of CELF2, a splicing factor involved in mRNA splicing, translation and editing, thus highlighting the indirect effect of ALKBH5 on splicing events in pancreatic cancer." (PMID 37850412, 2023).
pancreatic cancer (continued). "However, the mitoferrin proteins were upregulated in PDAC cells from pancreatic cancer patients despite the decreased expression of ALKBH5, again highlighting the likely complexity of mitoferrin regulation in vivo, particularly in cancer cells." (PMID 36359860, 2022). "For instance, ALKBH5 was reported to show highly expression in acute myeloid leukemia (AML) and to regulate the stability of AXL mRNA to maintain leukemia stem cell (LSC) function, nonetheless, recent reports have shown that ALKBH5 plays an inhibitory role in pancreatic cancer." (PMID 35114989, 2022). "In contrast, restoration or augmentation of ALKBH5 expression is a potential therapeutic strategy for the treatment of those cancers in which ALKBH5 plays a tumor-suppressive role, such as bladder cancer and pancreatic cancer." (PMID 35063010, 2022). "The m6A erasers FTO and ALKBH5 play roles in promoting pancreatic cancer." (PMID 35945641, 2022). "Moreover, Bo Tang and his colleagues revealed that the eraser ALKBH5 suppressed pancreatic cancer tumorigenesis through promoting transcription of WIF-1 mRNA and inhibiting Wnt signaling pathway in a m6A dependent manner." (PMID 36347025, 2022). "Additionally, dysregulation of ALKBH5 was found to mediate drug- or radio-resistance in GBM, oral squamous cell carcinoma, bladder cancer, pancreatic cancer and BRCA-mutated epithelial ovarian cancers." (PMID 35063010, 2022). "ALKBH5 is emerging as a potential drug-target for cancer, however, ALKBH5 overexpression is reported to inhibit several cancer cell types, including bladder and pancreatic cancers." (PMID 35333330, 2022). "Similarly, ALKBH5 also suppresses tumor progression in pancreatic cancer, lung cancer, and esophageal squamous cell carcinoma, with downstream targets such as PER1, YAP, and WIF-1." (PMID 35395767, 2022). "ALKBH5 suppresses pancreatic cancer tumorigenesis through mediation of Wnt pathway." (PMID 34603372, 2021). "Thus, we deduce that the protective role of ALKBH5 in pancreatic cancer is closely related to FBXL5-mediated regulation of iron metabolism." (PMID 34733841, 2021). "In previous research, up-regulating m6A demethylase ALKBH5 may enhance the sensitivity to gemcitabine in pancreatic cancer." (PMID 34603372, 2021). "ALKBH5 was positively correlated with PER1 expression in pancreatic cancer tissues and could prevent pancreatic cancer progression by increasing PER1 mRNA expression in a m6A-dependent manner." (PMID 34697563, 2021). "In conclusion, we screened alternations of ten m6A regulatory genes in the TCGA database of pancreatic cancer patients and identified that ALKBH5 was the most valuable prognosis-related gene that may be associated with AKT signaling pathways." (PMID 34055982, 2021). "However, another study revealed that ALKBH5 can inhibit cell migration and invasion in pancreatic cancer." (PMID 34659574, 2021). "Accordingly, we found that in pancreatic cancer cells, ALKBH5-overexpression led to reduction of intracellular iron levels, and this could be restored via FBXL5 knockdown." (PMID 34733841, 2021). "Compared with their study, we screened the 9 more m6A regulators and explored the CNV in the public database, evaluated the copy number variation (CNV) data of m6A on the OS and DFS of patients with PAAD, and further verified the prognostic value of ALKBH5 in pancreatic cancer." (PMID 34055982, 2021). "Our study not only demonstrated genetic characteristic changes of m6A-related genes in pancreatic cancer and found a strong relationship between the changes of ALKBH5 and poor prognosis but also provided a novel therapeutic target for pancreatic cancer therapy." (PMID 34055982, 2021). "Furthermore, we focused on ALKBH5 for intensive investigation of its molecular mechanism in protecting against pancreatic cancer." (PMID 34733841, 2021).
pancreatic cancer (continued). "The loss of ALKBH5 post-transcriptionally decreased the expression of PER1 in YTHDF2-dependent manner, and facilitated cell migration, invasion, proliferation and tumor growth in pancreatic cancer." (PMID 33593354, 2021). "In a research about pancreatic cancer, the expression of ALKBH5 was found downregulated in tumor cells and could inhibit cells by demethylating the lncRNA KCNK15-AS1, which can be used in prognostics and therapy strategies." (PMID 35003214, 2021). "Moreover, study revealed that the deletion of ALKBH5 decreased the infiltration of CD8+T cells, which linked m6A modification to the immune microenvironment of pancreatic cancer." (PMID 34345203, 2021). "In lung cancer, gastric cancer, and epithelial ovarian cancer, ALKBH5 may act as an oncogene, whereas in colon cancer and pancreatic cancer, ALKBH5 may inhibit tumor progression." (PMID 33428593, 2021). "Interestingly, in pancreatic cancer, ALKBH5 is downregulated, which decreases cancer cell motility owing to demethylation of the m6A target lncRNA KCNK15-AS1." (PMID 32709063, 2020). "This study aimed to explore the role of the m6A demethylase ALKBH5 in pancreatic cancer (PC)." (PMID 32429928, 2020). "ALKBH5 was downregulated in pancreatic cancer cells, and inhibited pancreatic cancer motility." (PMID 32742194, 2020). "In agreement with our study, some groups have reported that ALKBH5 could serve as a novel prognostic biomarker that predicts a poor prognosis in colorectal and pancreatic cancers." (PMID 32547941, 2020). "However, ALKBH5 overexpression sensitized pancreatic cancer cells to gemcitabine therapy and inhibited pancreatic cancer tumorigenesis by reducing the levels of m6A-dependent WNT inhibitory factor 1 (WIF-1) and hindering WNT signaling activation." (PMID 32398132, 2020). "ALKBH5 expression was noticed to be downregulated in pancreatic tumors." (PMID 33511112, 2020). "Conversely, ALKBH5 could inhibit tumor growth in bladder cancer and pancreatic cancer." (PMID 36347025, 2022). "Finally, an alteration of ALKBH5 was identified, which could be considered a biomarker for prognosis or a therapeutic target for pancreatic cancer therapy." (PMID 34055982, 2021). "Recent studies have revealed that certain m6A genes (e.g., RBM15, METTL14, FTO, and ALKBH5) are significantly associated with PAAD stage and that the expression level of ALKBH5 has a strong influence on the infiltration of CD8 + T cells in the immune microenvironment of pancreatic cancer." (PMID 34233576, 2021). "Additionally, m6A eraser ALKBH5 was down-regulated in pancreatic cancer cells, which could demethylate KCNK15-AS1 and regulate KCNK15-AS1-mediated cell motility and EMT process." (PMID 34211849, 2021). "ALKBH5 targets a lncRNA named KCNK15-AS1 via direct demethylation and is associated with inhibition of the pancreatic cancer metastasis, which might serve as a potential therapeutic target for pancreatic cancer patients." (PMID 33511112, 2020). "ALKBH5 upregulates Wnt inhibitory factor 1 (WIF‐1) expression by removing m6A of WIF‐1 mRNA and inhibits pancreatic cancer progression by suppressing the Wnt pathway." (PMID 40448344, 2025). "ALKBH5 also promotes Wnt inhibitory factor 1 (WIF-1) transcription, suppressing Wnt signaling in pancreatic cancer cells and inhibiting cancer progression." (PMID 38856795, 2024). "Conversely, the demethylase ALKBH5 is documented to control the expression of KCNK15-AS1 through demethylation, thereby mitigating the migratory and invasive capabilities of pancreatic cancer cells." (PMID 38255219, 2024). "ALKBH5 regulates WIF-1, PER1, and lncRNA KCNK15-AS1 expression in an m6A-dependent manner and inhibit the occurrence and progression of pancreatic cancer tumors." (PMID 35945641, 2022). "We further detected the mRNA expression levels of ALKBH5 and CELF2 in pancreatic cancer tissues, and found that the CELF2 expression level is positively correlated with the ALKBH5 expression level." (PMID 35941702, 2022).
pancreatic cancer (continued). "The demethylase ALKBH5 can also regulate the expression of KCNK15-AS1 via demethylation, which inhibits pancreatic cancer cell migration and invasion." (PMID 36581942, 2022). "Overall, our results reveal a previously uncharacterized mechanism of ALKBH5 in protecting against PDAC through modulating regulators of iron metabolism and underscore the multifaceted role of m6A in pancreatic cancer." (PMID 34733841, 2021). "Previous studies reported that METTL3, METTL14, FTO, ALKBH5 and YTHDF2 play important roles in pancreatic cancer cells." (PMID 34458141, 2021). "Upregulation of ALKBH5 or IGF2BP2 were both significantly associated with poor survival in several studies, highlighting the prognostic value of ALKBH5 and IGF2BP2 in pancreatic cancer." (PMID 34239358, 2021). "ALKBH5, a versatile RNA m6A demethylase efficiently demethylated KCNK15-AS1 in pancreatic cancer cells." (PMID 34178644, 2021). "Combining the downregulation of FBXL5 in pancreatic cancer samples and its positive correlation with survival, our results indicate that FBXL5, as a downstream target of ALKBH5, plays a vital role in protecting against pancreatic cancer." (PMID 34733841, 2021). "Other studies indicate that ALKBH5 decreases WIF-1 RNA methylation and inhibits pancreatic cancer tumorigenesis through the Wnt signaling pathway." (PMID 34332578, 2021). "Overall, these results indicated that ALKBH5-driven demethylation of KCNK15-AS1 dramatically reduced migratory and invasive potential of pancreatic cancer cells." (PMID 34178644, 2021). "A previous study reported that METTL3, ALKBH5 and YTHDF2 play important roles in pancreatic cancer cells." (PMID 32843065, 2020). "The absence of ALKBH5 significantly influences the detrimental clinicopathological characteristics observed in patients with pancreatic cancer." (PMID 39791162, 2025). "Additionally, ALKBH5 demethylates specific long non-coding RNAs (lncRNAs), such as KCNK15-AS1, which are downregulated in pancreatic cancer, leading to the migration and invasion of cancer cells." (PMID 39192357, 2024). "Therefore, ALKBH5, HDAC4 and HIF1α form a positive feedback loop in PC cells under hypoxic conditions and contribute to pancreatic cancer progression." (PMID 37149664, 2023). "Furthermore, pancreatic cancer patients with lower METTL3, METTL14, RBMX, FTO, ALKBH5, YTHDF1, and YTHDC1 mRNA expression levels or higher VIRMA, HNRNPA2B1, EIF3A, IGF2BP1, IGF2BP2, and IGF2BP3 mRNA expression levels had significantly poorer OS (P < 0.05)." (PMID 34330301, 2021). "Previous studies have reported that METTL3, METTL14, WTAP, FTO, ALKBH5, YTHDF2, and YTHDC1 play pivotal roles in regulating the proliferation, metastasis, and chemosensitivity of pancreatic cancer cells." (PMID 34733841, 2021). "The m6A eraser ALKBH5 could demethylate the lncRNA KCNK15-AS1 and inhibit KCNK15-AS1-mediated pancreatic cancer cell motility." (PMID 34497315, 2021). "In addition, ALKBH5 demethylates lncRNA KCNK15-AS1 and downregulates its expression in pancreatic cancer tissues, inhibiting cell motility and invasion." (PMID 35004679, 2021). "Moreover, ALKBH5 demethylated lncRNA KCNK15-AS1, which was downregulated in pancreatic cancer tissues compared with the normal tissues, thus elevating pancreatic cancer motility, including migration and invasion." (PMID 32742194, 2020). "However, ALKBH5 can also induce m6A demethylation of KCNK15-AS1, thereby upregulating KCNK15-AS1, which binds to the 5′UTR of KCNK15 to suppress its translation, thus inhibiting the growth of pancreatic cancer cells." (PMID 40271153, 2025).
pancreatic cancer (continued). "Furthermore, the demethylase AlkB homolog 5 (ALKBH5) can regulate the stability of potassium two-pore domain channel subfamily K member 15 (KCNK15)-AS1 via demethylation and inhibit the migration and invasion of pancreatic cancer cells." (PMID 36581942, 2022). "In addition, ALKBH5 posttranscriptionally activates period circadian regulator 1 (PER1) in an m6A-YTHDF2-dependent mechanism, with subsequent PER1 upregulation driving reactivation of the ATM–CHK2–CDC25C signaling cascade to suppress pancreatic cancer cell proliferation." (PMID 40986143, 2025). "After treated with gemcitabine, only METTL14 was significantly increased in all six pancreatic cancer cell lines, but not METTL3, WTAP, VIRMA, FTO or ALKBH5." (PMID 34458141, 2021).